TSHR (thyroid stimulating hormone receptor)
Diseases named in the same sentence as TSHR in open-access papers (continued):
Sharing a sentence is not in itself a finding about the gene and the disease.
viral infections (2 papers, 2021 to 2024). "Neutrophil activation derived autoantigens (MPO, PRTN3, and PADI4) were prominently increased in blood of both SARS-CoV-1 and SARS-CoV-2 viral infections, while TSHR and PTPRN2 autoantigens were specifically increased in SARS-CoV-2." (PMID 34276672, 2021).
amyloidosis (1 paper, 2021). A disorder characterized by the localized or diffuse accumulation of amyloid protein in various anatomic sites. "Antibodies anti-thyroid peroxidase, anti-thyroglobulin, and anti-TSHR were negative and amyloidosis was diagnosed on surgical sample of total thyroidectomy." (PMID 34063105, 2021).
Arrhythmia (1 paper, 2023). Any cardiac rhythm other than the normal sinus rhythm. "In addition, a combination of TSHR and TSHR autoantibodies, as well as amiodarone, a drug structurally similar to thyroid hormones for the treatment of arrhythmia, may also affect thyroid function." (PMID 38298184, 2023).
asthma (1 paper, 2022). "TSHR does not have a well‐established association to asthma and/or atopy, but human fibrocytes, whose increased number is implicated in asthma with chronic airflow obstruction, express the thyrotropin receptor." (PMID 35344303, 2022).
cardiac hypertrophy (1 paper, 2017). "Generation of TSHR binding cAMP-stimulatory antibodies, thyroid enlargement and alterations, elevated serum thyroxin levels, tachycardia and cardiac hypertrophy were maintained for at least 9 months in all Ad-TSHR-immunised mice." (PMID 27368808, 2017).
cardiomyopathy (1 paper, 2025). A disease of the heart muscle or myocardium proper. "However, unlike any other treatments currently available, specific elimination of autoreactive B cells can also stop Graves’ Eye Disease and cardiomyopathy that are caused by cross-reactivity of anti-TSHR autoantibodies with the eyes and heart, while avoiding compromising the immune system." (PMID 40264771, 2025). "Patients who suffer from Graves’ Eye Disease or cardiomyopathy, which do not have effective treatment options, would also benefit from TSHR CAAR T cell therapy, and the cost may be more justified in these cases." (PMID 40264771, 2025).
craniosynostosis (1 paper, 2025). Craniosynostosis is defined as the premature fusion of one or more cranial sutures leading to secondary distortion of skull shape resulting in skull deformities with a variable presentation. "Case 1 is a 4-year-old boy with craniosynostosis and mitral valve dysplasia with SNAH caused by a heterozygous TSHR variant c.1515C >A; p.S505R." (PMID 41064600, 2025).
endometriosis (1 paper, 2022). The growth of functional endometrial tissue in anatomic sites outside the uterine body. "A recent ex vivo study on thyroid transcripts in patients with endometriosis described an overexpression of TSHR and a decreased biosynthesis of T3 and an accumulation of T4 in ectopic endometrium." (PMID 34405378, 2022). "The relative risk of endometriosis is significantly increased in women tested positive for thyroperoxidase (TPO) antibodies, similarly a high prevalence of anti-TSHR antibodies, pathognomonic of Grave’s disease, is shown in patients with endometriosis." (PMID 34405378, 2022).
endothelial dysfunction (1 paper, 2018). In vascular diseases, endothelial dysfunction is a systemic pathological state of the endothelium (the inner lining of blood vessels) and can be broadly defined as an imbalance between vasodilating and vasoconstricting substances produced by (or acting on) the endothelium. "Some studies have shown that the TSH receptor (TSHR) is expressed in endothelial cells and increases the risk of endothelial dysfunction." (PMID 29440225, 2018).
enteritis (1 paper, 2021). Inflammation of the small intestine. "In addition, some studies have reported that Salmonella that can cause enteritis possesses an antigenic cluster similar to the thyroid stimulating hormone receptor protein, where antibodies against the thyrotropin receptor proteins might be produced after infection." (PMID 35069441, 2021).
experimental autoimmune encephalomyelitis (1 paper, 2021). An autoimmune demyelinating disease of the central nervous system that is produced experimentally in animals by the injection of homogenized brain or spinal cord in Freund's adjuvant. "These public T cell clones detected in pGD patients are potentially TSHR-specific and pathogenic similar to experimental autoimmune encephalomyelitis (EAE)-specific T cells with a shared Vβ8.2 segment." (PMID 33912135, 2021).
glioblastoma (1 paper, 2023). The most malignant astrocytic tumor (WHO grade IV). "Glioblastoma highly expresses TSHR and TSH in the tumor microenvironment promotes its proliferation, invasion and immune evasion, which limits the T cell killing of glioblastoma." (PMID 37538176, 2023).
liver dysfunction (1 paper, 2024). "The risk of liver dysfunction in GD increases with older age and higher titres of thyroid-stimulating hormone receptor antibody (TRAb)." (PMID 39598112, 2024).
mitral valve prolapse (1 paper, 2025). A fairly common and often benign valvular heart disorder characterized by redundancy or hooding of mitral valve leaflets so that they prolapse into the left atrium, often causing mitral regurgitation. "This is the first Indian case of genetically confirmed SNAH associated with the Asp633Glu TSHR mutation, presenting with previously undescribed extrathyroidal features (e.g., brachydactyly, ocular telecanthus, flat nasal bridge, mitral valve prolapse)." (PMID 41018437, 2025).
osteosarcoma (1 paper, 2020). A usually aggressive malignant bone-forming mesenchymal neoplasm, predominantly affecting adolescents and young adults. "We used U2OS cells derived from a moderately differentiated osteosarcoma stably overexpressing human TSHR (U2OS-TSHR cells) as a model of osteoblast precursors to investigate TSHR-mediated effects in bone differentiation in human cells." (PMID 32508750, 2020).
Pca (1 paper, 2022). "The results showed that the higher expression levels of JAZF1, PRDM6, RBMS3, and TSHR were correlated with the poor prognosis of Pca patients." (PMID 35959113, 2022). "In the regulatory networks of target genes of the sDMIRs, we found that JAZF1, PRDM6, RBMS3, and TSHR were correlated with the poor prognosis of PCa patients." (PMID 35959113, 2022).
periapical granuloma (1 paper, 2021). Chronic nonsuppurative inflammation of periapical tissue resulting from irritation following pulp disease or endodontic treatment. "In the periapical granuloma, PPARD gene was the highest alternative allele prediction from G>C (rs9794) with 1.0 polymorphism percentage in other African populations followed by TSHR with a polymorphism percentage of 0.94 from G>C (rs1991517) in the same population." (PMID 34539639, 2021). "In our study, datasets of the identified active genes revealed that periapical granulomas have the highest correlation with SNPs for PPARD, TSHR, and SLC16A1 in the African population." (PMID 34539639, 2021).
periodic paralysis (1 paper, 2024). "Therefore, screening for thyroid hormone and anti-thyroid stimulating hormone receptor antibody levels is necessary when treating patients with periodic paralysis." (PMID 39088436, 2024).
pituitary adenomas (1 paper, 2014). "TSHR (thyroid stimulating hormone receptor) is not normally considered a T-cell antigen, but mutations of this receptor have been associated with increased vasculature and the development of pituitary adenomas." (PMID 24959420, 2014).
poorly differentiated carcinoma of the thyroid (1 paper, 2016). "TSHR expression could be very low in DTC and even undetectable in poorly differentiated carcinoma of the thyroid." (PMID 26985248, 2016).
pulmonary hypertension (1 paper, 2015). Increased pressure within the pulmonary circulation due to lung or heart disorder. "The patients with pulmonary hypertension had significantly higher pulmonary vascular resistance (PVR), cardiac output and thyroid-stimulating hormone receptor antibody (TRAb) compared to those without (p < 0.001, p = 0.028 and p < 0.001, respectively)." (PMID 24838983, 2015).
schizophrenia (1 paper, 2021). A major psychotic disorder characterized by abnormalities in the perception or expression of reality. "The levels of antibody titer represent that thyroid peroxidase-antibody (TPOAb), thyroid-stimulating hormone receptor-antibody (TSHrAb), and thyroglobulin-antibody (TgAb) were raised in the patients suffering from schizophrenia along with thyroid dysfunction." (PMID 33995058, 2021).
squamous cell carcinoma (1 paper, 2020). A carcinoma arising from squamous epithelial cells. "The EDF genes specific for the histology subtype also include TSHR, KEAP1, and EGFR in adenocarcinoma, and NOTCH1, PIK3CA in squamous cell carcinoma." (PMID 33078899, 2020).
struma ovarii (1 paper, 2018). An ovarian mature teratoma characterized by the presence of aberrant thyroid tissue. "The mechanisms underlying the pathophysiology of functioning struma ovarii is suggested that struma ovarii is an autonomous hormone- secreting tumor or that the ovarian thyroid tissue is stimulated by thyroid-stimulating hormone receptor antibody." (PMID 30196119, 2018).
testis (1 paper, 2025). "The features observed in our studied families, including undescended testis and ophthalmic abnormalities, have also been reported in other studies in patients with CH in general and specifically in patients carrying different TSHR variants." (PMID 40391015, 2025).
tumor (77 papers, 1985 to 2025). "Elevated TSHR methylation was linked to larger tumor sizes and lymphovascular invasion, while increased miRNA-222-3p levels correlated with multifocality." (PMID 39125979, 2024). "Benign nodules were mainly associated with functional TSHR variants (19 [42%]) as evidenced by increased nodular sodium-iodide symporter expression and lower preoperative serum TSH levels (eFigure 4 in the Supplement)." (PMID 35679040, 2022). "Sanger sequencing of DNA extracted from the tumour tissue revealed a missense somatic mutation (c.1703T>C, p.Ile568Thr) in TSHR." (PMID 30416831, 2018). "The mechanism underlying the functioning status of the tumor is still unclear but the presence of thyroid stimulating hormone receptor (TSHR) is thought to play a role." (PMID 26530865, 2015). "The functional outcome is predicted for over a hundred thyroid stimulating hormone receptor (TSHR) mutations, as well as cancer related mutations in oncogenes or tumor suppressor genes." (PMID 26518340, 2015). "NIS mRNA levels have been linked to both TSHR mRNA and tumour marker Thyroglobulin mRNA levels." (PMID 37352166, 2023). "Also, TSHR methylation is associated with capsule rupture, extracapsular nodal extension, organ invasion, the middle-sized tumor (2<size<4 cm), well-differentiated carcinoma, and >5 nodes sampled." (PMID 37560303, 2023). "Patient and tumor characteristics of malignancies discovered within Afirma GSC-S TSHR variants." (PMID 36619548, 2022). "Most hyper-functioning tumors harbor both TSHR mutations and proto-oncogene mutations; this coexistence suggests that carcinomas arise from the activity of classical oncogenes, such as RAS and RET/PTC, and that the TSHR and Gs mutations contribute to the hyper-functioning features of the neoplasms." (PMID 28117293, 2017). "To identify TSHR‐positive DTC cell lines to serve as target cells for evaluating the specificity and anti‐tumor effectiveness of CAR‐T cells directed against TSHR, we examined the TSHR expression in the DTC cell lines, including TPC‐1, KTC‐1, and FTC‐133." (PMID 40985353, 2025). "Together, these findings highlight the multifaceted role of TSHR signaling in coordinating tumor cell proliferation, invasion, and metabolic adaptation." (PMID 41301693, 2025). "TSHR inhibitors have been shown to suppress tumor immune evasion by inhibiting programmed death-ligand 1 (PD-L1) expression and activating T effector cells." (PMID 40532044, 2025). "This approach leverages the exceptional tumor specificity of TSHR in thyroidectomized DTC patients and overcomes the immunogenicity barrier by employing the natural ligand." (PMID 40985353, 2025). "For instance, studies have shown a significant increase in promoter methylation of the TSHR gene in BRAF-mutated PTC samples, leading to gene silencing and subsequent tumor progression." (PMID 38949925, 2024). "Patients with larger tumor size (>2 cm) and lymphovascular invasion had significantly higher methylation levels of TSHR (p = 0.002 and p = 0.039, respectively)." (PMID 39125979, 2024). "TSHR signaling initiates carcinogenesis and cytokine production in tumor cells, influencing the tumor environment." (PMID 39125979, 2024). "Elevated TSHR methylation levels were shown to have a statistically significant weak positive correlation with larger tumor sizes and lymphovascular invasion." (PMID 39125979, 2024). "The age and invasion status, including the capsular, vascular, and extrathyroidal extensions, were closely related to TSHR expression in tumor tissues." (PMID 37208644, 2023).
tumor (continued). "A significant relationship between TSHR methylation and tumor diameter was also described in the meta-analysis, as the TSHR promoter methylation occurrence in patients with tumor diameter >2 cm was higher than in patients with tumor diameter ≤2 cm." (PMID 36013156, 2022). "Quantitative immunohistochemical analysis of tumor xenografts from nude mice showed that TSHR, NIS, TPO, and TG expression were all significantly reduced after overexpression of PC." (PMID 36266265, 2022). "We observed the interaction with TSHR-positive tumor cells induced rapid increase of ZAP70 and ERK activities within minutes, indicating antigen-dependent activation of the CAR-Jurkat T cells." (PMID 35252208, 2022). "To recognize TSHR-positive tumor cells, we constructed scFvs from two monoclonal antibodies, K1-70 and KSAb." (PMID 35252208, 2022). "Our findings also suggest that the TSHR methylation level was significantly higher in patients with larger tumor size." (PMID 36013156, 2022). "The TSHR methylation level was significantly higher in PTC with larger tumor size (>2 cm) compared to smaller (≤2 cm) tumor size (p < 0.001)." (PMID 36013156, 2022). "The TSHR methylation level was significantly higher in PTC with larger tumor size (>2 cm) compared to a smaller tumor size (≤2 cm) and in patients with lymph node metastases, lymphovascular invasion and multifocality." (PMID 36013156, 2022). "The TSH/TSHR cascade has been considered a pivotal modulator for carcinogenesis and/or tumor progression in these cancers." (PMID 32698392, 2020). "In PTCs, RUNX3 hypermethylation and TSHR hypomethylation were reported as related to tumor recurrence." (PMID 28938489, 2017). "Patients with high tumor TSHR expression levels had lower survival rates compared to patients with low TSHR tumor expression levels." (PMID 28439256, 2017). "As a result, some experiments in this study relied on exogenously expressed TSHR, which may exceed the levels of endogenously expressed TSHR in tumor cells from patients." (PMID 40985353, 2025). "However, the TSH‐reverse‐CAR‐T cells didn't exhibit effective antitumor activity against TSHR‐positive tumor cells compare to TSH‐CAR‐T cells." (PMID 40985353, 2025). "TSHR agonists have the dual effects of increasing the efficacy of radioactive iodine therapy and potentially accelerating tumor progression; moreover, even after TSH stimulation, 10–20% of DTC fails to concentrate sufficient radioactive iodine for effective treatment." (PMID 40532044, 2025). "CAR-T cells targeting TSHR effectively kill TSHR-positive tumor cells and inhibit tumor metastasis." (PMID 40532044, 2025). "The differences in analyzed miRNA expression and TSHR expression between cancerous tissue and normal tissue could help in understanding the biological behavior of the tumor." (PMID 39125979, 2024). "Moreover, TSH induced PD-L1 expression via the TSHR-JUN pathway and promoted the immunosuppressive environment of tumors, whereas TSHR inhibitors reversed tumor progression." (PMID 38275375, 2023). "This enabled a unique evaluation of the iodine avidity in primary tumour tissue, resected lymph node metastases, and comparison of avidity to the expression of iodine-transport related proteins (NIS, TPO, TSHR and pendrin), as well as mutations in the TERT promoter and codon V600 of the BRAF gene." (PMID 37352166, 2023). "The methylation level of TSHR correlated with total tumor size." (PMID 36013156, 2022). "The remarkable thyroid function shown in the current experiments with the TSHR-KO mice remaining euthyroid at 20 weeks indicates the potential longevity of this approach in contrast to the tumor formation we found earlier in transplants of unpurified cells into SCID mice." (PMID 34276566, 2021). "Peripheral blood (PB) thyroid stimulating hormone receptor (TSHR) mRNA is one of circulating tumor markers, while it remains unclear if it is affected by BRAF gene mutations." (PMID 29088773, 2017).